TBC1D22A (TBC1 domain family member 22A)
Description:
May act as a GTPase-activating protein for Rab family protein(s).
Synonyms: C22orf4; HSC79E021
Tractability: PROTAC: ubiquitination databases record sites on it; its protein half-life has been measured.
Gene: Protein-coding gene on chromosome 22 (46,762,617 to 47,175,699, forward strand). Ensembl gene ENSG00000054611.
Subcellular location (Human Protein Atlas): Golgi apparatus; Nucleoplasm; Vesicles
Gene Ontology:
Molecular function: 14-3-3 protein binding; protein binding; protein homodimerization activity; GTPase activator activity
Biological process: regulation of cilium assembly
Cellular component: Golgi apparatus
Genetic constraint (gnomAD): Loss-of-function variants: 40 observed, 59.07 expected, observed/expected ratio (o/e) 0.68, 90% interval 0.52 to 0.88. The upper end of that interval is the gene's LOEUF score, 0.88, which puts it in group 3 of 6, group 1 being the genes least tolerant of losing a copy. Missense variants: 622 observed, 696.81 expected, observed/expected ratio (o/e) 0.89, 90% interval 0.83 to 0.95. Synonymous variants: 300 observed, 280.56 expected, observed/expected ratio (o/e) 1.07, 90% interval 0.97 to 1.18.
Homologues: Orthologues: chimpanzee TBC1D22A (99% identical), macaque TBC1D22A (92% identical), dog TBC1D22A (91% identical), mouse Tbc1d22a (90% identical), rat Tbc1d22a (90% identical), guinea pig TBC1D22A (88% identical), pig TBC1D22A (87% identical), zebrafish tbc1d22a (72% identical), tropical clawed frog tbc1d22a (72% identical). Paralogues in human: TBC1D22B (61% identical), TBC1D16 (19% identical), TBC1D4 (18% identical), TBCK (18% identical), TBC1D1 (17% identical), TBC1D9B (17% identical), TBC1D15 (16% identical), RABGAP1 (16% identical), TBC1D9 (16% identical), RABGAP1L (16% identical), TBC1D2 (16% identical), TBC1D8B (16% identical), and 33 more.
Diseases named in the same sentence as TBC1D22A in open-access papers:
TBC1D22A is named in the same sentence as 20 diseases in open-access papers, as found by Europe PMC text mining. Sharing a sentence is not in itself a finding about the gene and the disease. The quoted sentences say what the papers report.
ovarian carcinoma (3 papers, 2023 to 2024). A malignant neoplasm originating from the surface ovarian epithelium. "In the univariate cox regression analysis, TBC1D22A (HR = 1.44299, p < 0.01) and age (HR = 1.01948, p < 0.01) appeared as risk factors for the prognosis of patients with ovarian cancer, and race (HR = 0.79663, p < 0.05) was a protective factor." (PMID 39439452, 2024). "Previously, we performed whole-exome sequencing on tissue samples from a cohort of patients with ovarian cancer and found that platinum-sensitive patients show a significantly higher missense mutation rate of TBC1D22A than platinum-resistant patients." (PMID 39439452, 2024). "The OS, PFS, DFS and DSS of patients with high and low expression of TBC1D22A were analyzed to assess the correlation between TBC1D22A expression and the prognosis of ovarian cancer." (PMID 39439452, 2024). "The findings indicated that elevated TBC1D22A expression was correlated with a poor outcome in ovarian cancer and served as a significant independent prognostic indicator." (PMID 39439452, 2024). "In fact, this study has certain limitations and more in vivo and in vitro experiments are necessary for revealing the carcinogenic mechanism of TBC1D22A in ovarian cancer, which we are planning to do in the future." (PMID 39439452, 2024). "For all we know, this research first reports the expression and prognostic value of TBC1D22A in ovarian cancer." (PMID 39439452, 2024). "The results of Western blot analysis also suggested that TBC1D22A was overexpressed in ovarian cancer." (PMID 39439452, 2024). "And the results indicated that the expression of TBC1D22A was higher in ovarian cancer, which was consistent with our findings." (PMID 39439452, 2024). "Subsequently, through a comprehensive exploration of the patient's clinical characteristics, it was proved that TBC1D22A was an independent prognostic factor for ovarian cancer." (PMID 39439452, 2024). "In conclusion, the expression of TBC1D22A in ovarian cancer and its relationship with prognosis, immune infiltration, and IC50 of first-line chemotherapy drugs were analyzed in an integrated way." (PMID 39439452, 2024). "Subsequently, we conducted univariate and multivariate regression analyzes to delve deeper into the prognostic significance of TBC1D22A in ovarian cancer." (PMID 39439452, 2024). "The protein level of CITED2, LYVE1, OGN, RAP1A, and TBC1D22A were higher in ovarian cancer tissues than that in normal tissues." (PMID 37784081, 2023). "The results showed that TBC1D22A was mainly expressed in the cytoplasm and nucleus, which was undetectable in normal ovarian tissues and showed moderate to low intensity staining in tissues of ovarian cancer." (PMID 39439452, 2024). "The research was aimed at evaluating whether TBC1D22A is an independent prognostic factor in ovarian cancer." (PMID 39439452, 2024). "The current research first demonstrated the high expression of TBC1D22A in ovarian cancer." (PMID 39439452, 2024). "Immune cell infiltration analysis showed that TBC1D22A could promote the enrichment of M2 macrophages in ovarian cancer tissues to exert an immunosuppressive effect, and ultimately promoted the progression of ovarian cancer." (PMID 39439452, 2024). "Therefore, combined use of TBC1D22A inhibitors may improve the effect of immune checkpoint blockade on ovarian cancer, and TBC1D22A may also act as a molecular marker for screening whether immune checkpoint blockade can be used." (PMID 39439452, 2024). "VPS13B, TBC1D22A, PPP3CA, CUX1 and PPP1R15A were identified as poor prognostic genes for cisplatin resistance in ovarian cancer, while PLGRKT, CDKAL1 and TAP1 were identified as good prognostic genes." (PMID 39103807, 2024). "VPS13B, TBC1D22A, PPP3CA, CUX1 and PPP1R15A were identified as poor prognostic genes of cisplatin resistance in ovarian cancer, while PLGRKT, CDKAL1 and TAP1 were identified as good prognostic genes." (PMID 39103807, 2024).
ovarian carcinoma (continued). "Through biological information screening, RT-qPCR and WB verification, it was found that VPS13B, TBC1D22A, PPP3CA, CUX1 and PPP1R15A were highly expressed in cisplatin-resistant tissues of ovarian cancer, while PLGRKT, CDKAL1 and TAP1 were low expressed." (PMID 39103807, 2024). "We then examined the expression of TBC1D22A mRNA in IOSE-80, COC1, ES-2 and SKOV3 cell lines and found higher expression in the COC1, ES-2 and SKOV3 ovarian cancer cell lines than in the normal ovarian cell line IOSE-80." (PMID 39439452, 2024). "Further analysis showed that ovarian cancer patients with high level of CITED2, LYVE1, OGN, RAP1A, and TBC1D22A had a poor prognosis that that with level of CITED2, LYVE1, OGN, RAP1A, and TBC1D22A (all p < 0.05)." (PMID 37784081, 2023). "The expression levels of VPS13B, TBC1D22A, PPP3CA, CUX1, and PPP1R15A genes were found to be up-regulated in ovarian tissue of cisplatin-resistant ovarian cancer patients compared to those with ovarian cancer." (PMID 39103807, 2024).
bipolar disorder (2 papers, 2023 to 2025). A disorder of the brain that causes unusual shifts in mood, energy, activity levels and the ability to carry out day-to-day tasks. "TBC1D22A has been associated with structural or functional abnormalities of the head or the central nervous system (CNS), such as seizures, schizophrenia, or bipolar disorder." (PMID 36980813, 2023).
Macrocephaly (2 papers, 2023 to 2025). Occipitofrontal (head) circumference greater than 97th centile compared to appropriate, age matched, sex-matched normal standards. "There are three genes that are proposed as the main candidates for macrocephaly (TBC1D22A, CELSR1, and GRAMD4) given their location in the highly associated genomic regions, proposed function, or high probability of loss of function intolerance." (PMID 36980813, 2023). "Interestingly, several genes within Region 2, including CERK, TBC1D22A, CELSR1, and GRAMD4 were found to be implicated in seizures, renal abnormalities, lymphedema, macrocephaly, and developmental delay in PMS." (PMID 40429797, 2025). "Regarding some functionality of these genes (TBC1D22A, CELSR1, and GRAMD4), we propose previously a region of 4.5 to 8 Mb from the telomere, strongly associated with macrocephaly in PMS, also supported by this study, and aligned with other works, suggesting to GRAMD4 associated with macrocephaly." (PMID 40429797, 2025).
epilepsy (1 paper, 2024). A brain disorder characterized by episodes of abnormally increased neuronal discharge resulting in transient episodes of sensory or motor neurological dysfunction, or psychic dysfunction. "TBC1D22A is a protein localized in the Golgi apparatus that plays a crucial role in preserving the integrity of the Golgi membrane and has been implicated in the pathogenesis of liver cancer, epilepsy and other diseases." (PMID 39103807, 2024).
esophageal carcinoma (1 paper, 2024). A primary or metastatic malignant neoplasm involving the esophagus. "By analyzing the pan-cancer data, it was found that TBC1D22A also has a prognostic value in esophageal carcinoma (ESCA) and liver hepatocellular carcinoma (LIHC), which needs further research in related fields." (PMID 39439452, 2024).
Hypotonia (1 paper, 2025). Hypotonia is an abnormally low muscle tone (the amount of tension or resistance to movement in a muscle). "Hypotonia and seizures were also significantly more frequent in individuals with larger deletions, particularly those affecting TBC1D22A and CELSR1 (χ2 = 18.734; degrees of freedom = 2; p < 0.001)." (PMID 40429797, 2025).
tobacco use disorder (1 paper, 2020). "Functional analysis showed the association of three genes (CDS2, TBC1D22A and WNK1) with tobacco use disorder." (PMID 32344947, 2020). "Three genes: CDS2, TBC1D22A, and WNK1 were connected to tobacco use disorder, which may be caused by the prevalence of smoking in 14.7% of CVD population (control group consists of non-smoking individuals)." (PMID 32344947, 2020).
cancer (4 papers, 2013 to 2025). A tumor composed of atypical neoplastic, often pleomorphic cells that invade other tissues. "We subsequently collected 22 pairs of cancer and adjacent tissues for immunohistochemical staining, and the results also showed that TBC1D22A was upregulated in cancer tissues." (PMID 39439452, 2024). "ELOVL7, PTDSS1, POLR1D, TBC1D22A, CCNC and TCF25 are some of the interesting genes with cancer related functions identified from the DES analysis." (PMID 24088394, 2013).
cardiovascular diseases (2 papers, 2020). "Analyzed genes were associated with cardiovascular diseases and risk factors (TBC1D22A, WNK1), bone mineral density (HDAC5), body weight (PABPC3), glycerophospholipid metabolism (CDS2), Notch signaling (HDAC5), RNA transport and degradation (PABPC3)." (PMID 32344947, 2020).
neurological diseases (1 paper, 2024). "The TBC1D22A (TBC1 domain family member 22A) gene interacts with 14-3-3 proteins, which play a crucial role in various neurological diseases." (PMID 39273692, 2024).
tumor (1 paper, 2024). "For a higher expression of TBC1D22A, tumor cells were likely to be well-differentiated." (PMID 39439452, 2024).
TBC1D22A also shares sentences with these, for which no sentence is quoted: schizophrenia (2 papers); dementia (1); developmental delay (1); liver cancer (1); lymphedema (1); Obesity (1); ovarian serous cystadenocarcinoma (1); Seizure (1); skin cutaneous melanoma (1).